RCN1 (reticulocalbin 1)
Diseases named in the same sentence as RCN1 in open-access papers (continued):
Sharing a sentence is not in itself a finding about the gene and the disease.
cancer (continued). "RCN1 suppresses ER stress‐induced apoptosis via calcium homeostasis and PERK–CHOP signalling in cancer cells." (PMID 34747128, 2021). "NUS1 and RCN1 were selected based on their significantly higher expression in OSCC tissues (more than twofold compared to adjacent non-cancerous tissue), supported by previous reports of their roles in other cancers." (PMID 40869423, 2025). "In this study, reticulocalbin-1 was significantly upregulated in all 24 examined cancer tissue samples in comparison to non-neoplastic kidney tissue." (PMID 40975763, 2025). "Furthermore, RCN1 induces sorafenib resistance and malignancy in HCC by activating cancer signaling pathways." (PMID 38475805, 2024). "HSPA5, RCN1, CLGN, and TXD15 need to be validated using an assay method compatible with use in a central lab (e.g., ELISA) in a large prospective study of patients with advanced-stage cancer before these proteins can be used to guide anticoagulation prophylaxis." (PMID 37651191, 2023). "Therefore, in the present study, we aimed to examine whether RCN1 participates in sorafenib resistance and hepatocarcinogenesis in HCC and to clarify the molecular mechanism of its role in this type of cancer." (PMID 34663798, 2021).
tumor (23 papers, 2010 to 2025). "The expression of RCN1 is very low in normal tissue but often high in ccRCC tumor cells, which predisposes it as a possible therapeutic target." (PMID 40975763, 2025). "A high level of RCN1 was associated with poor clinicopathological parameters, like high grading or high tumor stage." (PMID 40975763, 2025). "Reticulocalbin-1 (RCN1) has been found to be highly expressed in ccRCC tumor cells and associated with poor prognosis." (PMID 41035074, 2025). "Immunohistochemistry assays provided further confirmation of the high expression of DLK1 and RCN1 in tumour tissues, suggesting that they were associated with tumour progression." (PMID 39548559, 2024). "We observed that high levels of RCN1 were significantly associated with a larger tumor size, microvascular invasion and higher TNM stage." (PMID 34663798, 2021). "In addition, we investigated the effect of RCN1 on the polarization of tumor-associated macrophages (TAMs)." (PMID 38713738, 2024). "Previously, our results suggested that RCN1 was associated with tumor metastasis." (PMID 38713738, 2024). "Reticulocalbin1 (RCN1) is implicated in tumorigenesis and tumour progression." (PMID 34747128, 2021). "Our findings showed that elevated RCN1 expression was linked to poor prognosis in LUAD patients, indicating that RCN1 acts as a risk factor in tumours." (PMID 39828988, 2025). "About ten years later, the influence of tumor-infiltrating regulatory T cells on the prognosis of ccRCC was analyzed and a correlation between the overall survival, Treg-cell infiltration and RCN1 was determined." (PMID 40975763, 2025). "In vitro functional analysis was performed by silencing RCN1 using siRNA in Caki-1 and A498 cell lines to determine its role in tumor cell behavior." (PMID 40975763, 2025). "We also have to acknowledge a possible influence of tumor environment, e.g. the influence of regulatory T-cells on ccRCC and its interaction with RCN1, which cannot be examined in a cell-line model." (PMID 40975763, 2025). "Another possible therapeutic approach is to use the high expression of reticulocalbin-1 as a target for an antibody–drug-conjugate, benefiting from the homogenous distribution in all tumor cells." (PMID 40975763, 2025). "We conducted in vitro experiments downregulating RCN1 in ccRCC cell lines to elucidate the potential role of RCN1 in tumor aggressiveness in ccRCC." (PMID 40975763, 2025). "RCN1 is proposed to play a significant role in the prognosis of HCV-HCC via inhibition of tumor invasion and migration, suggesting a potential prognostic biomarker ability for this gene." (PMID 38475805, 2024). "Subsequently, our experimental results also confirmed that knockdown of RCN1 can promote tumor cell apoptosis." (PMID 38713738, 2024). "To investigate the role of RCN1 in the tumor microenvironment, we first analyzed the effect of RCN1 expression on tumor-infiltrating immune cells using the GSE53625 dataset." (PMID 38713738, 2024). "Our analysis of tumor-infiltrating immune cells found that the expression of M2 macrophages was positively correlated with RCN1." (PMID 38713738, 2024). "The upregulation of RCN1 in tumour tissues compared to normal oral mucosal tissues is associated with a poor prognosis and can be utilized as a prognostic indicator for OSCC." (PMID 38057406, 2023). "Our future research will focus on conducting animal experiments to further investigate the effects of RCN1 on tumours in vivo and explore the potential molecular mechanisms underlying RCN1-mediated TAMs M2 polarization in the TME." (PMID 38057406, 2023). "The effect of tumour cell-derived RCN1 on the polarization of THP-1 macrophages was investigated by establishing a coculture model of THP-1 macrophages and OSCC cells." (PMID 38057406, 2023). "Although RCN1 is expressed in endothelial cells, the increase of RCN1 expression is indicative of tumor characteristics." (PMID 35436915, 2022).
tumor (continued). "Using the GEPIA website, we found that RCN1 expression was significantly higher in tumor tissues than in the adjacent tissues." (PMID 34663798, 2021). "Recently, several studies have revealed that RCN1 acts as an oncogene involved in tumor progression." (PMID 34722631, 2021). "RCN1 proteins can not only have intrinsic roles in tumor development but also serve as a regulator involved in immune-related activities." (PMID 34722631, 2021). "Examination of clinical tumor tissues using IHC also proved that the expression of RCN1 was positively correlated with that of PCNA (n = 68)." (PMID 34663798, 2021). "We could confirm that the RCN1 level correlated significantly and positively with tumor grading (p = 0.002), pT stage (p = 0.036), presence of lymph node metastases (p = 0.004) and distant metastases (p = 0.017)." (PMID 40975763, 2025). "Another gene, RCN1, a calcium‐binding protein located in the endoplasmic reticulum (ER) and a member of the CREC family, has been associated with both tumour formation and tumour progression." (PMID 39828988, 2025). "RCN1 is highly expressed in few glands especially in the gonads, tissues with terminal differentiation like muscle cells and neurons, and activated fibroblasts in inflammatory tissue as well as in tumor surrounding tissue." (PMID 40975763, 2025). "Furthermore, high RCN1 expression was correlated with higher tumor grade (p = 0.002), tumor stage (p = 0.036), presence of lymph node metastases (p = 0.004), and distant metastases (p = 0.017)." (PMID 40975763, 2025). "The protumour genes DLK1 and RCN1 were highly expressed in the CNVhigh area, which might be related to tumour progression and could be targeted for precision therapy." (PMID 39548559, 2024). "In addition, RCN1 downregulation in human AML cells significantly inhibited tumor growth in the NSG mouse xenograft model." (PMID 37746742, 2023). "Therefore, the aim of this study was to investigate the effects of RCN1 on the biological behaviour of OSCC and the regulation of tumour-associated macrophage (TAM) polarization." (PMID 38057406, 2023). "RCN1 served as a biomarkers for tumor diagnosis and prognosis." (PMID 35436915, 2022). "Our analysis showed that RCN1 may be an independent predictor of tumor recurrence and overall survival." (PMID 34663798, 2021). "RCN1 has been drawn intensive attention due to its role in tumorigenesis and tumour progression." (PMID 34747128, 2021). "Additional studies will also be necessary to investigate the role of RCN1 in tumor stromal cells." (PMID 34663798, 2021). "RCN1 appears as a potential renal cell carcinoma tumour marker in clinical proteomic analysis." (PMID 34747128, 2021). "Additionally, silencing RCN1 led to a significant reduction in tumor cell migration and invasion." (PMID 40975763, 2025). "In addition, the RCN1 mRNA expression increased significantly with the tumor grading." (PMID 40975763, 2025). "By conducting a differential analysis based on the transcriptional expression patterns of the CNVhigh and CNVlow regions, we further identified crucial genes related to tumour progression, such as DLK1 and RCN1." (PMID 39548559, 2024). "HCV miRNAs target RCN1 to regulate EMT in HCV-HCC, thereby acting as a tumor suppressor by inhibiting invasion and migration in HCV-HCC." (PMID 38475805, 2024). "This study therefore explores a novel mechanism by which RCN1 promotes tumour progression and suggests that RCN1 inhibition will be an effective strategy for the treatment of OSCC driven by high RCN1 expression." (PMID 38057406, 2023). "Subsequently, we collected several clinical GBM tumor tissues and detected the expression levels of HLA-DMA, P4HB and RCN1 in GBM via qRT-PCR and IHC assays." (PMID 35436915, 2022). "To further elucidate the role of RCN1 in HCC, we examined RCN1 expression in HCC tumor tissues and matched tumor-adjacent tissues (n = 68)." (PMID 34663798, 2021).
tumor (continued). "Our study proposes for the first time that RCN1 can activate the UPR under certain circumstances and promote tumor cell survival instead of inhibiting PERK-CHOP-mediated UPR signaling during ER stress." (PMID 34663798, 2021). "Here, we found that RCN1, an endoplasmic reticulum resident protein, is significantly upregulated in sorafenib-resistant HCC cells and promotes tumor progression." (PMID 34663798, 2021). "Tumour growth and bone resorption were measured in a nude mouse model bearing NCI‐H1299 cells transduced with shRNA/RCN1 vector using in vivo imaging technique and micro‐CT." (PMID 34747128, 2021). "Apart from WDR1, several other oncoproteins and tumour suppressors, such as LDHA, CLIC1, ARPC5, ZYX, RCN1, FHIT and CFTR, were identified in this study." (PMID 32601462, 2020). "Recent studies have shown that RCN1 plays a tumor-promoting role in tumor progression; however, the role of RCN1 in ESCC has not yet been studied." (PMID 38713738, 2024). "Our data showed that the downregulation of RCN1 affects the viability of HaCaT cells, although it is not a tumor cell line." (PMID 37746742, 2023).
RCN1 also shares sentences with these, for which no sentence is quoted: colon carcinoma (3 papers); aniridia (2); Alzheimer disease (1); cecum adenocarcinoma (1); colon adenocarcinoma (1); colon adenoma (1); colon mucinous adenocarcinoma (1); endometrial cancer (1); esophageal cancer (1); gastric cancer (1); genetic diseases (1); Hepatitis (1); limb-girdle muscular dystrophy (1); lung adenocarcinoma (1); metastasis (1); microphthalmia (1); myosclerosis (1); nervous system diseases (1); pancreatic adenocarcinoma (1); rectal adenocarcinoma (1); rectal adenoma (1); rectal mucinous adenocarcinoma (1); rectosigmoid adenocarcinoma (1); renal carcinoma (1); small cell carcinoma (1); uterine sarcoma (1); Wilms tumor (1).